SIRT1 (sirtuin 1)
Diseases named in the same sentence as SIRT1 in open-access papers (continued):
Sharing a sentence is not in itself a finding about the gene and the disease.
Sepsis (continued). "Our study results imply that celecoxib is effective in controlling inflammatory response by the activation of SIRT1, inhibiting inflammatory protein COX-2, and NF-κB pathways in polymicrobial sepsis murine model and helping antibiotic in clearing the bacterial load." (PMID 28533769, 2017). "However, the real cellular target of salidroside for SIRT1-regulated NF-κB activation inhibition and HMGB1 nucleocytoplasmic translocation inhibition during sepsis still needs to be clarified in the future." (PMID 28931916, 2017). "The different expression of miRNA might potentially be used to discriminate septic AKI from sepsis-non AKI and they were correlated with the regulation of mitochondrial oxidative stress and dysfunction, including PGC-1α, SIRT1, mTOR, OXSR1 and NOX5." (PMID 28296904, 2017). "To determine whether SIRT1 is involved in the pathogenesis of sepsis-induced AKI, we studied both the activity and protein expression of SIRT1 in renal tissue." (PMID 28003866, 2016). "Based on the importance of the SIRT1/3 axis in the pathogenesis of severe shock, we hypothesized that SIRT3 may play a role in sepsis." (PMID 28003866, 2016). "Interestingly, the relationship between the functions of nuclear SIRT1 and mitochondrial SIRT3 is coordinated during the hypoinflammatory phase of sepsis in THP1 human promonocytes." (PMID 28003866, 2016). "This suggests that chiglitazar alleviates sepsis-induced NAD+ depletion not by merely compensating for SIRT1 substrate demand in the cytoplasm but through metabolic reprogramming that redirects NAD+ toward sustaining mitochondrial respiration and redox homeostasis." (PMID 40422869, 2025). "This suggests that other inducers of SIRT1 expression could be effective in ARDS and sepsis." (PMID 40470379, 2025). "Mechanistically, these phenomena can be attributed to the LXR agonists enhancing SIRT1 signaling, thereby boosting the antioxidant level of FOXO1 and resistance to endoplasmic reticulum stress, as well as deacetylating NF-κB, which in turn mitigates sepsis-induced myocardial injury and dysfunction." (PMID 38690282, 2024). "Its expression is typically subdued in the initial stages of sepsis, yet the heightened glycolysis triggered by the intense inflammatory response can lead to an accumulation of niacinamide adenine dinucleotide (NAD+), thereby promoting the upregulation of SIRT1 expression." (PMID 39234245, 2024). "SIRT1 reduces the expression of inflammatory cytokines by directly deacetylating the NF-κB inhibitory subunit, while SIRT3 mainly alleviates oxidative stress-induced damage by maintaining mitochondrial function and enhancing the activity of antioxidative enzymes, improving sepsis-induced MODS." (PMID 38690282, 2024). "Similarly, NBP might be an ideal approach for sepsis, IBD, RA, cancer, and autoimmune encephalomyelitis as its ability to target HIF-1α, AMPK/SIRT1, PI3K/Ak, and Nrf-2/HO-1." (PMID 35422893, 2022). "This study proved that the levels of SIRT1, PGC-1α, UCP2, TFAM, and COXIV all decreased in septic mice, the effect of which was reconciled by nanoFe treatment (vs. the CLP group, B P < 0.05), indicating the positive role of nanoFe in improving mitochondrial biogenesis during sepsis." (PMID 36064371, 2022). "In conclusion, this study demonstrates that the SIRT1/PGC-1α/PPAR-γ axis plays an important role in the process of MAR1 in reducing LPS-induced inflammation in in vitro sepsis model and provides clues for further exploring the mechanism of MAR1 in reducing inflammation in sepsis." (PMID 33557833, 2021). "The current research showed that in the setting of sepsis-induced AKI, THC could protect renal function and attenuate AKI by suppressing oxidative stress and inflammation, which might be mediated by activating the SIRT1 signaling pathway." (PMID 34187277, 2021). "Furthermore, SIRT1 did not correlate with gram-negative bacteria, gram-positive bacteria, anaerobes, fungus, mycoplasmas, or total culture (all P>0.05) in sepsis patients." (PMID 33263643, 2020).
Sepsis (continued). "Herein, we summarize the published papers concerning the beneficial effects of SIRT1 inhibition (not activation) on sepsis treatment, which may help us better understand the detailed mechanism and potential application of SIRT1 in the treatment of sepsis." (PMID 30533222, 2018). "In addition, SIRT1 plays a role in mediating the inflammatory response, and its relationship to 2′-O-GH during sepsis has not been studied." (PMID 29997508, 2018). "Just in a human monocyte cell model of endotoxin tolerance and human leukocytes from sepsis, SIRT1 expression was not reduced but rather increased, which may be due to the elevated NAD (+) levels." (PMID 30533222, 2018). "However, the specific mechanisms through which SIRT1 regulates sepsis and the relationship between SIRT1 and Notch signaling remain poorly elucidated." (PMID 29867921, 2018). "SIRT1 should not always be activated or repressed during sepsis treatment." (PMID 30533222, 2018). "Salidroside significantly and effectively upregulated SIRT1 expression, inhibited the inflammatory cascade reaction, decreased the NF-κB activation and HMGB1 nucleocytoplasmic translocation, reduced the severity of acute lung injury, and improved the survival rate during sepsis." (PMID 28931916, 2017). "Moreover, we reported that SIRT1 modulates the E-selectin and ICAM-1 expression during sepsis." (PMID 28503576, 2017). "In contrast, some reports have claimed that SIRT1 inhibition, but not activation, could be a novel way to treat sepsis in its hypoinflammatory phase." (PMID 28003866, 2016). "Thus, SIRT-2 and not SIRT-1 expression was increased during hypo-inflammatory phase of ob/ob-sepsis mice." (PMID 27500833, 2016). "Finally, we demonstrate that mice lacking SIRT1 expression in myeloid cells are resistant to endotoxin-induced hypothermia, but succumb to gram-positive bacteremia/sepsis and gram-negative endotoxemia/shock with similar kinetics as WT mice." (PMID 24386389, 2013). "However, the absence of SIRT1 promotes Akt acetylation, consequently enhancing the production of inflammatory factors in murine macrophages, potentially exacerbating the progression of sepsis in mice." (PMID 39234245, 2024). "However, it is not clear whether SIRT1 signal is involved in the regulation of melatonin on ALI induced by sepsis." (PMID 33362546, 2020). "Moreover, we also did not define how long the effects on SIRT1 on reversing global immunity might last, an important issue in translating this concept to human sepsis." (PMID 30069485, 2018). "However, the role of SIRT1/3 on mitochondrial protection following sepsis is not reported." (PMID 28003866, 2016). "Thus, the data suggest that SIRT-2 and not SIRT-1 plays a crucial role in ob/ob mice with sepsis." (PMID 27500833, 2016). "Unlike SIRT1 and SIRT2, SIRT3 activation and overexpression show several positive effects in sepsis treatment." (PMID 30533222, 2018). "e. decreased SIRT-1 and increased SIRT2 expression during the hypo-inflammatory phase in the liver tissue of ob/ob mice with sepsis (not shown)." (PMID 27500833, 2016).
type 2 diabetes (226 papers, 2008 to 2026). "VK2 achieves this by activating the AMPK/SIRT1 signaling pathway to ameliorate type 2 diabetes-associated osteoporosis (T2DOP) and suppress ferroptosis." (PMID 40678144, 2025). "Emerging evidence also supports the potential of SIRT1 as a clinical marker of osteoporosis risk, as shown in a study involving patients with newly diagnosed type 2 diabetes." (PMID 41009597, 2025). "Given that SIRT-1 is implicated in the epigenetic regulation of pathogenic pathways in several disorders, including type 2 diabetes." (PMID 38001474, 2023). "In the pathogenesis of OA, Silent Information Regulator 2 type 1 (SIRT1) has been identified to related to age-associated diseases, such as diabetes type II, Alzheimers and osteoporosis." (PMID 35501316, 2022). "A number of studies showed that SIRT1 and its polymorphisms are involved in visceral obesity, which can lead to type 2 diabetes." (PMID 33577446, 2021). "A significant interaction was found between two SIRT1 SNPs (rs7895833 and rs1467568) and exposure to famine in utero on the risk of type 2 diabetes." (PMID 33435147, 2021). "The NAD+-dependent deacetylase Sirt1 has been implicated in the prevention of many age-related diseases, including cancer, type 2 diabetes, and cardiovascular disease." (PMID 34216621, 2021). "Though no other groups have reported direct associations of rs497849 to age-dependent cognition, SIRT1 genotypes have been linked to age and lifestyle-associated traits including cognition, carcinoma, type-2 diabetes and body mass index." (PMID 32242137, 2020). "The correlation between the level of sirtuins and oxidative stress has also been demonstrated in patients with type 2 diabetes, in which increased Sirt1 expression was associated with increased serum TAC levels." (PMID 33396247, 2020). "Currently, clinical trials are being conducted for SIRT1 activators in the treatment of age-associated diseases and type 2 diabetes." (PMID 33021962, 2020). "Previous studies showed that Sirt1 expression in blood cells is involved in diseases associated with systemic chronic inflammatory processes such as coronary artery disease, type 2 diabetes." (PMID 27784320, 2016). "Several synthetic SIRT1 activators have been recently developed for the treatment of age-associated diseases, including type 2 diabetes." (PMID 23989608, 2013). "Small molecule activators of SIRT1 have been identified that exhibit efficacy in animal models of diseases typically associated with aging including type 2 diabetes." (PMID 19284563, 2009). "The identification of specific SNPs associated with type 2 diabetes comorbid depression paves the way for personalized medicine approaches, where SIRT1-targeted therapies might be developed to manage or mitigate the effects of this comorbidity." (PMID 39612426, 2024). "SIRT1 signaling has been associated with aging, caloric intake, and immune responses, and consistently, SIRT1 has also been associated with various age-associated diseases such as neurodegenerative diseases, type II diabetes, and immune-associated diseases." (PMID 36339585, 2022). "The present study shows that formononetin possess antidiabetic effect in high fat diet and low dose streptozotocin induced type 2 diabetes in experimental rats which may be linked with increase in expression of SIRT1." (PMID 30072892, 2018). "To investigate the relevance of SIRT1 for human metabolism and caloric restriction, we analyzed SIRT1 genetic variants in respect to the outcome of a controlled lifestyle intervention in Caucasians at risk for type 2 diabetes." (PMID 19014491, 2008). "Authors concluded that SIRT1 may be an important genetic factor involved in fetal programming during malnutrition, influencing type 2 diabetes risk later in life and proving to be an interesting diagnostic or prognostic marker of the development of such diseases." (PMID 33435147, 2021).
type 2 diabetes (continued). "Mechanically, the deacetylation of PGC-1α or FOXO1 modulated by SIRT1 is tightly linked with enhanced transcriptional activation in gluconeogenesis and glycolysis, resulting in increased hepatic glucose production and further contributing to the development of type 2 diabetes." (PMID 34738906, 2021). "However, there is little information on whether DR ameliorates nephropathy in type 2 diabetes, and if so, whether the effects of DR are associated with Sirt1 through anti-inflammatory function or through the regulation of autophagy." (PMID 21949662, 2011). "Alternatively, Sirt1 activation has been shown to have beneficial metabolic effects in type 2 diabetes." (PMID 40766326, 2025). "This study aimed to evaluate the effect of adding fenofibrate versus curcumin on weight, glycemic status, lipids profile, high-sensitivity C-reactive protein (hs-CRP), fetuin-A, and sirtuin 1 in patients with type 2 diabetes treated with glimepiride." (PMID 40481568, 2025). "This study investigated the dysregulation of key NAD+ salvage enzymes (CD38, NAMPT, and SIRT1) across albuminuria stages in type 2 diabetes (T2D)." (PMID 41470091, 2025). "In this study, we compare the effects of adding fenofibrate versus curcumin to glimepiride versus glimepiride alone on weight, glycemic status, lipid profile, hs-CRP, fetuin-A, and sirtuin 1 in patients with type 2 diabetes." (PMID 40481568, 2025). "A randomized clinical trial evaluated the effects of resveratrol (RV) supplementation on oxidative stress markers and sirtuin 1 levels in older adults with type 2 diabetes." (PMID 40563357, 2025). "At the same time, there were differences in the genotype distribution frequencies of rs12415800, rs3758391, and rs932658 in the SIRT1 gene between patients with type 2 diabetes comorbid depression and patients with type 2 diabetes without depression." (PMID 39612426, 2024). "In type 2 diabetes patients, due to the down-regulation of SIRT1 expression level, the neuroprotective effect was reduced, and depressive behaviors were increased, which further led to type 2 diabetes comorbid depression." (PMID 39612426, 2024). "The study selected 11 SNP sites of the SIRT1 gene and conducted correlation analysis to explore whether there were differences in the distribution frequencies of SNP site genotypes and alleles in patients with type 2 diabetes and type 2 diabetes comorbid depression." (PMID 39612426, 2024). "Highly specific Sirt1 activator, like SRT2104, was associated with a moderate improvement in arterial stiffness in type 2 diabetes." (PMID 38818612, 2024). "At the same time, this study will increase the detection of the SIRT1 gene locus to further clarify the effect of the SIRT1 locus gene on type 2 diabetes comorbid depression." (PMID 39612426, 2024). "Since current research on SIRT1 gene expression in patients with type 2 diabetes is limited, further research is needed." (PMID 39612426, 2024). "Meanwhile, Wang and Tong found that oral administration of resveratrol increased monocyte SIRT1 levels, increased insulin sensitivity, and decreased blood glucose in patients with type 2 diabetes mellitus complicated with coronary heart disease." (PMID 39062982, 2024). "Numerous factors influence the presence of depression in patients with type 2 diabetes, with the SIRT1 gene playing a significant role, serving as a potential biomarker for this comorbidity." (PMID 39612426, 2024). "The SIRT1 gene had 3 sites: rs12415800, rs3758391, and rs932658, which were related to the patient’s type 2 diabetes comorbid depression." (PMID 39612426, 2024). "The study used logistic regression analysis to analyze 11 SNP sites in the SIRT1 gene and type 2 diabetes comorbid depression." (PMID 39612426, 2024). "SIRT1 plays a major role in many human diseases, such as type 2 diabetes, rheumatoid arthritis, and cancers." (PMID 39466748, 2024).
type 2 diabetes (continued). "The present study aims to assess the effect of coadministration of glimepiride as a hypoglycemic drug and omega-3 fatty acids on the blood levels of irisin, sirtuin-1, glucose homeostasis, and lipid profile of type 2 diabetic patients." (PMID 38001474, 2023). "Liraglutide appears to improve the metabolic profiles of obese type 2 diabetic patients and increase Sirtuin 1(SIRT1) expression, which in turn appears to suppress the pro-inflammatory NF-kB pathway." (PMID 37266425, 2023). "This study suggested that in patients with type 2 diabetes, the deregulation of ADAM17 and MMP9 activities in atherosclerotic plaques is associated with an impaired expression of TIMP3 via SIRT1." (PMID 38304233, 2023). "The present study aims to assess the effect of coadministration of omega-3 fatty acids and glimepiride as a hypoglycemic drug on the blood levels of irisin, sirtuin-1, glucose homeostasis, and the lipid profile of type 2 diabetic patients." (PMID 38001474, 2023). "Some studies have reported that up-regulated expression of SIRT1 hinders the formation and development of pancreatic tissue fibrosis in type 2 diabetes in rats." (PMID 37240813, 2023). "In a mouse model of type-2 diabetes, Sirt1 activation inhibited microglial activation by upregulating BDNF." (PMID 36725745, 2023). "Curcumin can inhibit apoptosis via Sirt1-Foxo1 signalling in rats with type 2 diabetes and enhances lipid metabolism in adipocytes by promoting AMPK activity by activating SIRT1." (PMID 36815979, 2023). "By regulating insulin secretion and protecting pancreatic β-cells, SIRT1 protects cells from oxidative stress and inflammation and has become a therapeutic target in the prevention of type 2 diabetes." (PMID 36552538, 2022). "Because sirtuins and NAD+ have a well-established role in cardiovascular and metabolic diseases, there is compelling experimental and clinical evidence that boosting SIRT1 activity can help treat type 2 diabetes and dyslipidemia." (PMID 36361416, 2022). "A correlation between SIRT1 expression and irisin serum levels has been reported in type 2 diabetic patients and mice, suggesting the involvement of SIRT1 in PGC-1α-mediated irisin release." (PMID 35250605, 2022). "The treatment of obese type 2 diabetes patients with vitamin D also induces higher serum levels of SIRT1 and irisin, further pointing to the SIRT1-mediated release of irisin." (PMID 35250605, 2022). "Previous studies have shown that N1-methylnicotinamide (MNAM) regulates insulin sensitivity and hepatocyte gluconeogenesis in mice with type 2 diabetes by activating SIRT1 and inhibiting the acetylation of FOXO1." (PMID 36295866, 2022). "In vivo, AMPK/Sirt1 activity was reduced and ROS was increased in kidney tissue in a mouse model of type 2 diabetes." (PMID 34439446, 2021). "To verify the relationship between miR-204 and SIRT1, firstly we detected the mRNA and protein levels of SIRT1 in the islet tissue of type 2 diabetic mice and in the MIN6 cell injury model induced by palmitic acid." (PMID 34630099, 2021). "Currently, there are 71 clinical trials focusing on the effects of SIRT1 on various disorders, including vascular system injuries, coronary artery disease, aging, and type 2 diabetes." (PMID 34681756, 2021). "Further studies are required to clarify the signaling axis effects and analyze the protein structure of TET1 targeting SIRT1, providing more precise targets for the clinical therapy to type 2 diabetes or metabolism-related diseases." (PMID 34738906, 2021). "In conclusion, the results of this study indicated that eight weeks of supplementation with EA, 180 mg/day, reduced the levels of blood sugar, Insulin, IR, and Fetuin-A and increased SIRT1 in patients with type 2 diabetes." (PMID 33546744, 2021).